AHR (aryl hydrocarbon receptor)
Diseases named in the same sentence as AHR in open-access papers (continued):
Sharing a sentence is not in itself a finding about the gene and the disease.
colitis (continued). "Having established that HQD engages the microbiota–indole axis to restore barrier integrity and attenuate DSS colitis, we next asked whether this axis is linked to AhR activation and ISC differentiation." (PMID 41530817, 2026). "In summary, downregulation of epithelial cell–specific AhR and BD‐1 could promote the survival and interaction of colitis‐causing bacterial species with host epithelial cells." (PMID 40410944, 2025). "Furthermore, CH223191 (AhR inhibitor) was used to determine the underlying protective mechanism of myricetin on DSS-induced colitis." (PMID 39974840, 2025). "Also, treatment of anti‐CD40‐induced colitis mice with I3C caused an increase in the expression of AhR and mBD‐1." (PMID 40410944, 2025). "Interestingly, Card9-deficient mice were found to be susceptible to colitis due to impaired tryptophan metabolism, mitigating the formation of aryl hydrocarbon receptor (AHR) ligands." (PMID 40671790, 2025). "Because AhR and BD‐1 are important tumor suppressors, inhibiting them may also promote colitis‐associated tumorigenic transformation." (PMID 40410944, 2025). "As a result, AhR signaling pathway was suggested to be the underlying mechanism by which myricetin could exhibit the protection against colitis." (PMID 39974840, 2025). "Mice with a specific deletion of AHR in DCs are highly susceptible to DSS-induced colitis." (PMID 38674118, 2024). "AhR activation by natural AhR ligands (e.g., I3C) has been shown to prevent pathogenic gut microbial dysbiosis by altering gut microbiome composition in murine colitis." (PMID 39767818, 2024). "Based on the 16S rRNA microbial profiles of males and females in the current report, it appears that while there were obvious sex differences, Bacteroides appear to be associated with colitis induction and was regulated by AhR, though more prominently in females." (PMID 39229279, 2024). "Using macrophage-specific AhR-deficient mice, we found that AhR△mye mice developed severe colitis on DSS treatment, characterized by a significant increase in macrophage pyroptosis and subsequent IL-1β release in colon tissues, compared with AhRfl/fl littermates." (PMID 39113799, 2024). "The GM obtained from IBD patients showed poor ability to produce AhR ligands, and in addition, sterile mice susceptible to colitis observed significant improvement in intestinal inflammation after supplementation with AhR agonists and Lactobacillus strains capable of metabolizing tryptophan." (PMID 38318507, 2023). "Loss of IL-22 is associated with altered microbiome composition and function as well as reduced AhR activation, suggesting potential involvement in a host-microbe feedback loop in the gut that, combined, may increase susceptibility to colitis." (PMID 36894983, 2023). "Naringenin activates AHR, causing naive T cells to differentiate into Treg cells while inhibiting differentiation into Th17 and Th1 cells, increasing the ratio of Treg cells in the peripheral blood of mice with colitis and thus alleviating colitis." (PMID 37179416, 2023). "Gut dysbiosis in Card9-deficient mice decreases AhR activation and hinders recovery from colitis." (PMID 34062869, 2021). "Furthermore, berberine alleviates DSS-induced colitis by activating AhR, which adjusts the tryptophan metabolite levels associated with the gut microbiota." (PMID 35046810, 2021). "For instance, AHR knockout (ahr-/-) mice exhibit extensive abnormalities in vascular, hepatic, skin, bladder, and hematopoietic functions, increased susceptibility to experimentally induced colitis, and exhibit higher prevalence of intestinal tumorigenesis." (PMID 34149693, 2021). "Although AHR signaling has long been recognized to be implicated in the pathogenesis of autoimmune disorders, such as rheumatoid arthritis (RA), colitis, and systemic lupus erythematosus (SLE), its effect on the pathogenesis of type 1 diabetes (T1D) remains less understood." (PMID 32849515, 2020).
colitis (continued). "One clue might come from a study that looked at the impact of AhR allele on the ability of dietary broccoli to suppress colitis." (PMID 33552063, 2020). "Studies have shown an increased susceptibility to experimental colitis in AhR-deficient mice compared to control mice, suggesting that a deficiency in AhR ligands, followed by a lack of AhR activation in the intestine, may worsen inflammation." (PMID 32957545, 2020). "Similarly, our studies also showed that increased susceptibility to TNBS-induced colitis in AhR−/− mice compared to wild type." (PMID 30626868, 2019). "Moreover, the therapeutic effect of these two derivatives on ongoing colitis was abrogated in AhR-deficient mice." (PMID 31772949, 2019). "Consistently, histologic examination of colonic tissues revealed that activation of AhR with either Ficz or each of the two derivatives led to attenuation of colitis, which was associated with a significant reduction of IFN-γ and TNF-α and up-regulation of IL-22 RNA expression." (PMID 31031628, 2019). "Moreover, in multiple experimental mouse models of colitis, administration of Ficz subsequently caused IL-22 induction, whereas administration of an AhR antagonist resulted in more severe colitis with decreased IL-22 production." (PMID 26793707, 2015). "Importantly, our studies also demonstrated that AhR‐mediated induction of BD‐1 is involved in the regulation of the gut microbiome because in vivo blocking of BD‐1 prevented AhR ligands from reversing colitis‐associated microbial dysbiosis and colonic inflammation." (PMID 40410944, 2025). "Further evidence supporting this hypothesis includes a decrease in the kynurenine pathway in these patients, diminished AhR expression in inflamed mucosal samples obtained from individuals with CD, and a deficiency in dietary tryptophan linked to exacerbated colitis in murine models." (PMID 38543132, 2024). "However, resveratrol (3,4,5-trihydroxy-trans-stilbene), an AHR antagonist and naturally occurring compound found in the skin of red grapes and in red wine, suppresses inflammation and colon cancer associated with colitis in rodents." (PMID 35055106, 2022). "On the one hand, the loss of AHR may lead to a systemic inflammatory response as AhR null mice were highly susceptible to autoimmunity diseases, such as dextran sodium sulfate-induced colitis and experimental autoimmune encephalomyelitis." (PMID 30090104, 2018). "It alleviates DSS-induced colitis by activating aryl hydrocarbon receptor (AhR) signaling and promoting FOXP3+ Treg differentiation, and reduces pro-inflammatory NF-κB activity in IL-10-/- mice through a pirin-like protein." (PMID 41572837, 2026). "As an endogenous ligand of aryl hydrocarbon receptor (AhR), IAld can alleviate colitis in mice via AhR-dependent mechanisms, primarily by maintaining intestinal homeostasis." (PMID 40665732, 2026). "Growth of Lactobacillus not only boosts IAM and indole-3-lactate generation but also potentiates AhR signalling and attenuates colitis." (PMID 41530817, 2026). "In our study, we focused on a representative gut microbiota-derived Trp metabolite IAld, which serves as an important ligand for AhR and has been reported to have significant effects in alleviating colitis in mice." (PMID 40665732, 2026). "Collectively, these data establish that HQD alleviates murine colitis by activating AhR signaling to drive ISC differentiation." (PMID 41530817, 2026). "The aryl hydrocarbon receptor is a ligand-dependent transcription factor known for its ability to suppress inflammatory responses and attenuate experimental colitis." (PMID 41009721, 2025). "AhR-mediated induction of α-defensin 1 in colitis mice reversed the gut microbial dysbiosis and alleviated colitis." (PMID 39894796, 2025).
colitis (continued). "In summary, these findings demonstrate that L. paracaseiL21 and its postbiotic mitigate colitis by enhancing SCFA-mediated activation of AhR/HIF1α signaling, thereby promoting IL-22-dependent mucin synthesis and goblet cell regeneration." (PMID 40806121, 2025). "To investigate the impact of AhR‐mediated induction of mBD‐1 expression on colitis, we generated conditional AhR knockout mice in vil1‐expressing CECs using the cre‐flox system." (PMID 40410944, 2025). "Ameliorated colitis through AhR signaling activation, increased the expression of anti-inflammatory cytokines, and resulted in the expansion of IL-10-producing CD4+ T cells and IL-22-producing CD3−RORγt+ cells, but not CD4+Foxp3+ regulatory T cells." (PMID 40756994, 2025). "Sonia Mohanta found that AhR-/- mice exhibited a pronounced Th17 response in a DSS-induced colitis model." (PMID 40825672, 2025). "Conversely, administering an AhR antagonist to mice worsens TNBS-induced colitis, suggesting that AhR activation can mitigate intestinal inflammation, thus proposing AhR as a ‘new target’ for IBD treatment." (PMID 41031160, 2025). "Among these, we focused on the aryl hydrocarbon receptor (AhR) since its activation has been shown to ameliorate experimental colitis." (PMID 40487746, 2025). "One study aiming to identify the link between intestinal epithelial cells (IECs) and AHR in mitigating colitis showed that I3C enhanced mucin proteins, thereby promoting goblet cell development in wild-type mice that have colitis." (PMID 40094833, 2025). "Our data raised an important question about the potential biological impact of α-defensin 1 induction by AhR activation in colitis mice models." (PMID 39894796, 2025). "Our results revealed that the microbiota population from colitis mice treated with I3C dramatically elevated AhR and α-defensin 1 expression." (PMID 39894796, 2025). "In a mouse model of TNBS-induced colitis, Higher levels of IL-22 were observed in dendritic cells (DCs) with AhR activation mediated by 6-formylindole [3,2-b] carbazole (FICZ)." (PMID 41019044, 2025). "Our analysis found that decreased expression of AhR protein and α-defensin 1 was found in ileal tissue from CD patients, and intestinal epithelial cells (IECs) from various colitis mice modes." (PMID 39894796, 2025). "Multiple lines of colitis mice models and cell‐based experiments demonstrated that I3C treatment activates AhR, which directly binds to the DREs in the mBD‐1 promoter, leading to the induction of mBD‐1 expression in CECs." (PMID 40410944, 2025). "During inflammatory conditions, such as colitis, metabolites from this pathway can modulate the immune response by activating the aryl hydrocarbon receptor (AhR)." (PMID 40362027, 2025). "Experiments involving BD‐1 neutralization in vivo demonstrated that AhR‐mediated BD‐1 induction plays a critical role in preventing dysbiosis and colonic inflammation during colitis." (PMID 40410944, 2025). "This indicated that from the perspective of regulating Trp metabolism, A. muciniphila, pasteurized A. muciniphila, or Amuc_1100 predominantly alleviated colitis in mice by inhibiting the Kyn pathway, activating the indole pathway, and enhancing AhR signaling." (PMID 41488633, 2025). "Ba. uniformis degraded β-glucan and produced nicotinamide that promoted growth of Lb. johnsonii, which produced indole-3-lactic acid that activated the aryl hydrocarbon receptor, which was responsible for colitis mitigation." (PMID 41178959, 2025). "In a preclinical study, mice were administered 3% dextran sodium sulfate (DSS) to induce colitis and treated with an AhR agonist." (PMID 41009721, 2025). "Our findings provide a novel link between epithelial cell signaling involving AhR and induction of antimicrobial peptides such as BD‐1 with dysbiosis, colonic inflammation, and colitis." (PMID 40410944, 2025).
colitis (continued). "As an example, oral gavage with live Alistipes onderdonkii mitigated dextran sulfate sodium (DSS)‐induced colitis in mice by activating the aromatic hydrocarbon receptor (AhR) signaling pathway." (PMID 40236773, 2025). "Our data demonstrated that AhR transcriptionally regulates the production and secretion of antimicrobial BD‐1, which limits gut dysbiosis and attenuates colitis." (PMID 40410944, 2025). "Oral administration of I3LA in a DSS‐induced colitis model has previously been shown to activate the AhR pathway and improve intestinal mucosal integrity." (PMID 40856156, 2025). "We also analyzed the expression of α-defensin 1 in IECs from IEC-specific conditional AhR knockout mice (AhRΔIEC), and wild-type (WT) mice having colitis induced by DSS." (PMID 39894796, 2025). "AhR activation during colitis has also been shown to downregulate the mucosal immune response by modulating many other signaling pathways." (PMID 39894796, 2025). "Our analyses in AhR downregulated cells and IEC-specific conditional AhR knockout mice (AhRΔIEC)-having colitis induced by DSS demonstrated diminished ability to induce α-defensin 1 mRNA and protein expression upon I3C treatment." (PMID 39894796, 2025). "This is also supported by the current study in which we found that the colonic microbiota from colitis mice when cultured with CECs, significantly downregulated the expression of AhR and BD1 when compared to the controls." (PMID 40410944, 2025). "The results indicated that AhR deficiency increased susceptibility to colitis, while AhR activation using FICZ (a known agonist) mitigated DSS-induced colitis via the MK2/p-MK2/TTP pathway." (PMID 41009721, 2025). "Our analysis consistently found a more robust decrease in AhR and α-defensin 1 protein levels in colitis vs control mice and cells treated vs untreated with DSS, when compared to the data generated using mRNA analysis." (PMID 39894796, 2025). "Further focusing on AhR and mBD‐1, the data showed that the epithelial cells from anti‐CD40‐induced colitis mice exhibited decreased levels of AhR and mBD‐1 mRNA and protein expression when compared to the controls." (PMID 40410944, 2025). "The results indicate the role of impaired AhR signaling leading to decreased BD‐1 induction in promoting the development of colitis." (PMID 40410944, 2025). "Collectively, these findings indicated that mBD‐1 induced following AhR activation plays a critical role in the attenuation of colitis in vivo." (PMID 40410944, 2025). "Taken together, our findings suggested that AhR activation by I3C treatment in colitis mice reverses microbial dysbiosis and attenuates colitis." (PMID 39894796, 2025). "IL-7, alone or synergizing with IL-1β or IL-23, can also increase IL-22 production in ILC3s via aryl hydrocarbon receptor (AhR) and STAT3, and eventually promote colitis-associated colon cancer progression." (PMID 41467015, 2025). "This synergistic protection was validated in the DSS colitis model, in which AhR/PXR double-knockout mice exhibited more severe epithelial damage than single knockouts (an 80% vs. 40% increase in pathology score, p < 0.01)." (PMID 40825672, 2025). "Previous studies have shown that microbe-derived indole derivatives exert various effects, such as anti-inflammatory and antitumor effects, and can protect against colitis by activating AhR." (PMID 40342298, 2025). "AhR activation also regulates gut microbiota composition, which plays a significant role in the regulation of colitis." (PMID 40410944, 2025). "And AhR agonists are able to attenuate symptoms of the dextran sulfate sodium (DSS)-induced colitis in model mice by upregulating the expression of IL-22, and this model is highly similar to human UC." (PMID 41019044, 2025). "To further mechanistically characterize the role of AhR and mBD‐1, we extended the human studies in the murine models of colitis." (PMID 40410944, 2025).
colitis (continued). "I3C supplementation to SAMP/YitFc mice with spontaneous ileitis showed significant recovery in epithelial abnormalities, suggesting that I3C mitigated the colitis and gut dysbiosis through the activation of AhR." (PMID 40094833, 2025). "This review indicated that IN alleviates colitis by activating AhR signaling and inhibiting STAT1/STAT3 signals and IL-10." (PMID 40756994, 2025). "We previously reported that an aryl hydrocarbon receptor (AhR) ligand, indole-3-carbinol (I3C), was effective at reducing colitis severity through immune cell-mediated interleukin-22 (IL-22) production." (PMID 38397081, 2024). "The current report takes this a step further by illustrating that cell-specific expression of AhR in IECs plays a prominent role in the reduction in colitis severity during I3C treatment." (PMID 38397081, 2024). "Mulberry bark-derived extracellular vesicles also protect mice from colitis by activating the Aryl hydrocarbon receptor (AhR) signaling pathway mediated by heat shock protein family A member 8 (HSPA8)." (PMID 38545101, 2024). "Collectively, this report highlights the cell and sex-specific role of AhR in regulating microbes that can impact colitis disease." (PMID 39229279, 2024). "AhR signaling upregulates IL-22 production to produce antimicrobial peptides and inhibit inflammation and colitis in the gastrointestinal tracts of mice." (PMID 38790988, 2024). "I3C activates the Aryl hydrocarbon receptor (AHR) protein for the prevention of colitis and colon cancer." (PMID 39830328, 2024). "Provision of DIM to the diet has been shown to ameliorate DSS-induced colitis through AhR-dependent immunoregulatory and lymphogenic pathways, as well as through downregulation of inflammatory cytokines implicated in TLT formation." (PMID 39337636, 2024). "So, the altered faecal microbiota following Pg administration resulted in aggravated colon inflammation mediated through decreased metabolite LA production, which alleviated the Th17/Treg cell imbalance in an AHR-dependent manner during colitis progression." (PMID 38388542, 2024). "FICZ has been demonstrated to improve dextran sulphate sodium (DSS)-induced colitis by reducing IL-6 expression and increasing the expression of tight junction proteins via the activation of the AhR." (PMID 38473179, 2024). "The AhR antagonist StemRegenin 1 essentially abrogated the ameliorative effect of 5HIAA on colitis, as reflected by body weight, DAI, colon length, serum levels of IL‐22 and IL‐10, and colon histology." (PMID 38882491, 2024). "One such therapeutic target showing promise in the IBD research field is the aryl hydrocarbon receptor (AhR), which when targeted in colitis models by various exogeneous and endogenous ligands often reduces disease severity." (PMID 39229279, 2024). "Comparing WT to IEC-specific AhR knockout mice (AhRΔIEC), the results showed that AhR expression was essential in IECs for I3C-mediated protection during colitis." (PMID 38397081, 2024). "Administration of FICZ, a ligand of AHR can increase IL-22 expression that prevents and even heals colitis." (PMID 38542367, 2024). "To this end, we used IEC-specific AhR deletion coupled with a mouse model of dextran sodium sulfate (DSS)-induced colitis to understand how dietary AhR ligand 3, 3′-diindolylmethane (DIM) influenced TLT formation." (PMID 39337636, 2024). "Overall, these findings suggest an AhR-driven regulation in functional Tregs, as shown by protective effects of AhR activation in morbid conditions including colitis, diabetes, and experimental autoimmune encephalomyelitis." (PMID 39211042, 2024). "Conversely, supplementation with β-napthoflavone, an AhR agonist, accelerated recovery from colitis." (PMID 38448800, 2024). "In DSS-induced colitis mice, indole-3-acetic acid can also regulate the AhR/NRF2/NLRP3 pathway to alleviate intestinal inflammation and barrier function damage." (PMID 39334766, 2024).